IL33 (interleukin 33)
Diseases named in the same sentence as IL33 in open-access papers (continued):
Sharing a sentence is not in itself a finding about the gene and the disease.
cancer (continued). "IL-33 exerts multifunction in cancer progression besides cell proliferation such as immunomodulatory functions by producing chemokines, promoting inflammatory responses, driving Th2-type immune responses, and enhancing cancer stem-like properties." (PMID 30119635, 2018). "IL-33 and/or ILC2s therefore may have important therapeutic utility amongst the constellation of cancer immunotherapies that are currently emerging." (PMID 29440650, 2018). "The increasing amount of evidence implies that IL-33-triggered signals may be involved in cancer progression." (PMID 30119635, 2018). "In patient tissues, IL-33 expression in CAFs correlated with IL-33 expression in cancer cells." (PMID 30205617, 2018). "Recent studies identify IL-33 as an important pro-cancer factor." (PMID 28978138, 2017). "IL-33 has been shown to affect various immune cells during the inflammation and cancer development." (PMID 28710436, 2017). "To further validate these findings, we studied PDGF-BB-promoted cancer metastasis in Il33−/− mice." (PMID 27150562, 2016). "We will highlight which cells produce and which cells are activated by IL-33 in cancer." (PMID 28119694, 2016). "Indeed, IL-33 has been shown to promote potent cancer-specific effector and memory T cell immunity when used as an adjuvant for DNA vaccination in mice." (PMID 28119694, 2016). "Finally, we will discuss the issues to be addressed first before potentially targeting the IL-33 pathway for cancer therapy." (PMID 28119694, 2016). "Future studies may provide support that IL-33 down-regulation is a common thread in other carcinomas." (PMID 27619158, 2016). "Interleukin-33 (IL-33) is a cytokine of the IL-1 family and found overexpressed in various cancers." (PMID 26456994, 2015). "It has been reported that IL-33 was overexpressed in various cancers." (PMID 26456994, 2015). "Interestingly, IL-33 expression in serum and cancer tissues was contrary when comparing with ER and HER2 expression, although with statistical significance." (PMID 24778632, 2014). "Thus, the data on the role of IL-33 in cancer progression was limited, and in particular, the function mediated by IL-33 in human BC is under-investigated." (PMID 24778632, 2014). "In cancer tissues, expression of IL-33 was higher than matched normal breast tissues from the same patients, and was also associated with a well-differentiated phenotype, HER2 overexpression, more lymph nodes involvement, and a family history of malignant carcinoma." (PMID 24778632, 2014). "However, few data have been reported about the role of IL-33/ST2 axis in cancer, and little is known about the function of IL-33 in patients with BC." (PMID 24778632, 2014). "The tissue expression of IL-33 is significantly different, indicated that in carcinomas, immune cells may be recruited to anti-inflammatory and subsequent immunosuppression in HER2 overexpression tumors." (PMID 24778632, 2014). "Moreover, in carcinoma tissues, IL-33 expression is significantly higher in HER2-overexpressing tissues, consistent with the report that its receptor sST2 is over-expressed to promote BC metastases upon ErbB2 activation in BC cell lines." (PMID 24778632, 2014). "The EC-derived cytokines IL-33 and TSLP have been shown to enhance tumorigenesis by promoting epithelial-mesenchycmal transition (EMT) in organotypic culture of ex vivo carcinoma-associated fibroblasts (CAFs) and squamous cell carcinoma cells and by enhancing Th2 inflammation." (PMID 25101088, 2014). "IL-33 has also been reported to be elevated in lung tissues of K-ras transgenic mice, which are prone to tumorigenesis and cancer, in endothelial cells from several distinct human tumors, and in cancer epithelial cell lines." (PMID 23062310, 2012). "Therefore, targeting the IL-33/ST2 axis is a promising strategy for cancer immunotherapy." (PMID 39925809, 2025). "Indeed, previous studies on IL-33 in cancer have yielded somewhat opposing results as to whether it is pro- or anti-tumorigenic." (PMID 39931535, 2025).
cancer (continued). "Interestingly, Tregs accumulation in the TME can also be mediated by the IL-33/ST2 axis, further indicating this IL-33/ST2 axis may be a potential target for enhancing cancer therapy." (PMID 40216748, 2025). "Additionally, interleukin 33 (IL-33) has been shown to regulate Tregs in the context of cancer." (PMID 41394821, 2025). "In addition, IL‐33+ Venous‐1 is involved in cell communication with the cancer‐pre subcluster." (PMID 40860436, 2025). "Thus, the diverse effects of IL-33 on cancer may depend on its localization in the tissue, including epithelial cells, fibroblasts, versus immune cells." (PMID 38816352, 2024). "Moreover, Kudo‐Saito found that IL33 is a key driver of treatment resistance of cancer." (PMID 38923705, 2024). "First, direct injection of IL-33 into cancer patients could be considered." (PMID 38825642, 2024). "Therefore, IL-33 production by cancer cells creates a positive feedback loop, increasing the number of immune cells with suppressive phenotypes and promoting drug-resistant cancer stem cells." (PMID 39206193, 2024). "Furthermore, we sought to elucidate the role of IL33 across various cancers." (PMID 38923705, 2024). "In addition, we did not obtain any data from studies in America, Africa and Oceania, and a series of factors that affect the serum levels of IL-33 in cancer patients, including age, sex, and disease progression, could cause heterogeneity." (PMID 37507682, 2023). "Similarly, type 2 immunity-related cytokines IL-25 and IL-33 with recently characterised roles in cancer may either promote or suppress tumorigenesis in a context-dependent manner." (PMID 37455828, 2023). "Our findings suggest that IL-33 may serve as a plausible candidate for predicting 5-FU chemosensitivity and favorable prognoses, as well as a promising adjuvant to generate effective T cell-mediated protective immunity against cancer." (PMID 37056569, 2023). "IL-33 may similarly promote or inhibit cancer in a context-dependent manner." (PMID 37455828, 2023). "Consequently, we examine how targeting the inhibition of IL-25, IL-33 and type 2 intestinal immunity, to release the brakes on type 1 anti-cancer immunity, may be beneficial in certain CRC subtypes, but detrimental in others." (PMID 36263033, 2022). "In the state of injury, necrosis, or cell stress, IL-33 is released into the extracellular space and binds to its cognate receptor interleukin-1 receptor-like 1 (IL1RL1), which has been associated with tissue and metabolic homeostasis, inflammation, infection, and cancer." (PMID 34023857, 2021). "Finally, IL-33 modulates PD-1/PD-L1 expression in the cancer microenvironment, and preliminary studies suggest that co-targeting of IL-33 and immune checkpoint receptors may improve the outcomes of immunotherapy." (PMID 34572318, 2021). "Extending these data to clinical practice suggests that modulating the TME by targeting the IL-33/CXCR4 signaling circuit may attenuate the aggressiveness of cancer cells and provide a novel therapeutic strategy in precision medicine to improve the prognosis in HNSCC patients." (PMID 34298657, 2021). "IL-33/ST2 signaling activates myeloid differentiation primary response 88 (MyD88)/interleukin-1 receptor (IL-1R) associated kinase (IRAK)/TNF receptor-associated factor 6 (TRAF6) pathway in the majority of cell types, including cancer cells, stromal cells, and immune cells." (PMID 34209038, 2021). "Therefore, although targeting IL-33/ST2 is a potential treatment for a variety of diseases, including cancers, greater understanding of the mechanisms of the IL-33/ST2 pathway in macrophage polarization is required before clinical applications can be considered." (PMID 33628592, 2021). "Thus, targeting the IL‐33‐macrophage‐MMP‐9 signaling may provide a generalized therapeutic paradigm for treating a broad spectrum of cancer types." (PMID 34486239, 2021).
cancer (continued). "It has been suggested that TLS from cancer patients may contribute to the pathogenesis of CIAKI; therefore, Ravichandran and colleagues repeated the same experiments on IL-33 deficiency in cisplatin-treated mice without cancer." (PMID 33805488, 2021). "Whether and how IL-33 can affect TRM in cancer warrants investigation." (PMID 33329534, 2020). "Emerging data indicate that IL-33 may modulate the PD-1/PD-L1 axis also in cancer." (PMID 33329534, 2020). "Therefore, the role of IL-33 in cancer remains controversial." (PMID 33308251, 2020). "Thus, activation of ILC2s with IL-33 may be a strategy to increase immunotherapy efficacy in ILC2-infiltrated cancers." (PMID 33329534, 2020). "And most of the 24 DEPs (CDK1, SFN, PRKAR2B, MKI67 and MDK involved in the cell cycle; LOXL2, P4HA1, P4HA2, SPRX, DES, PRPH and CALML3 involved in construction and regulation of extracellular matrix; IL33 and EHD3 may involve in immune) were linked to cancer hallmarks." (PMID 33200655, 2020). "Notably, IL-33 is implicated in the differentiation of T cells into tissue-resident memory T (TRM) cells, a recently identified CD8+ T cell population found in various human cancers and correlating with favorable outcome." (PMID 33329534, 2020). "Increased IL-33 expression was also observed in primary epidermal keratinocytes from HrasG12S/+ mice after Dfb stimulation, which is similar to the reports that the activation of RAS/MAPK signaling was associated with increased IL-33 expression in cancer cells." (PMID 32792500, 2020). "The presence of IL-33 could be detected in both cancer cells and CAFs in human CCA tissues." (PMID 33046978, 2020). "Thus, locally released IL33 may support the development of HNSCC both directly through stimulation of cancer cell proliferation and indirectly though pro-angiogenic effects as well as suppression of potentially anticancer immune reactivity." (PMID 33066437, 2020). "The plasma IL-33 levels of these patients were not linked to the immunostaining of cancer cells." (PMID 31130612, 2019). "In contrast, far less is currently understood concerning the role of more recently identified members of this family in cancer such as IL-33 and IL-37, although such data that is available also indicates that these may have both pro- and anti- tumorigenic effects." (PMID 31231372, 2019). "Taken together these studies indicate that downregulation of the IL-33/ST2 axis in epithelial cells is tightly associated with tumorigenesis and metastasis, suggesting that retaining IL-33/ST2 expression in these cells might inhibit cancer progression." (PMID 31231372, 2019). "However, the role of the IL-33/ST2 axis has recently been related to cancers, in which the deletion of ST2 signaling may enhance the antitumor immune response." (PMID 31130612, 2019). "Therefore, our results confer preliminary new insights into the influence of IL-33/ST2 signaling in SCC progression and support the idea that IL-33 may be an important target for neoadjuvant treatments for cancer." (PMID 30112116, 2018). "Recent studies revealed that IL-33 could directly regulate cancer cells." (PMID 30119635, 2018). "Hence, IL-33 is correlated with a bad prognosis in these types of cancer." (PMID 30416507, 2018). "Taken together, IL-33 may promote cancer development and metastasis through different pathways." (PMID 30619376, 2018). "Therefore, further work is required to clarify the role of IL-33 in cancer." (PMID 30426271, 2018). "For instance, recent progression has uncovered important roles of IL-33 in the stimulation of regulatory T cell (Treg) expansion and function, whereas Tregs are important for the establishment and maintenance of immunosuppressive and immune tolerance in patients with cancers." (PMID 30559604, 2018). "Interestingly, our perspectives in IL-33 has now extended beyond its previous identification as an inducer of immune responses to that of a potency in chronic inflammation and timely activation by malignancies." (PMID 30619376, 2018).
cancer (continued). "However, recent findings have shown a role of IL-33 in several cancers where it may exert multiple functions." (PMID 28119694, 2016). "Finally, recent findings have revealed an important contribution of IL-33 to several cancers, where it may exert pro and—less frequently—anti-tumorigenic functions." (PMID 28119694, 2016). "Furthermore, IL-33 may also serve as a novel adjuvant in vaccination against cancer and infectious diseases." (PMID 26688508, 2016). "There are other evidences that IL-33 and sST2 may be involved in the pathogenesis of cancer." (PMID 24636276, 2014). "It has been reported that serum levels of sST2, which acts as a decoy molecule in the IL-33/ST2 pathway and represents another parameter of this study, vary among different cancer types." (PMID 41614943, 2026). "The protumoral microenvironment is sustained by IL-33, IL-18, and PGD2, which are, at least in part, secreted by PCa cancer cells supporting the recruitment, proliferation, and function of ILC2s." (PMID 40247153, 2025). "In cancer models, CD103+ DCs, activated by IL-33, stimulate CD8+ T-cell activity, leading to anticancer responses." (PMID 40305195, 2025). "In view of the importance of the IL-33/ST2 axis in the immunopathogenesis of esophageal inflammatory diseases and cancers, this review summarizes recent progress in this research field based on current published data." (PMID 40520454, 2025). "The IL-33/ST2 signalling pathway, a key player in type 2 inflammation, is increasingly recognized for its pro-tumoral roles in various cancers, contributing to immune evasion and metastasis." (PMID 41284319, 2025). "Its dual ability to promote both active protective immunity and immunosuppression positions IL-33/ST2 axis as a therapeutic target in diseases marked by immune dysregulation, including cancer." (PMID 41284319, 2025). "Here we investigate the physiological role of the IL-33/ST2 axis in skin homeostasis and cancer development." (PMID 40517383, 2025). "For example, IL-33-activates eosinophils that release more effector molecules, through the CD11b/CD18 link, essential for cancer cell death." (PMID 40305195, 2025). "IL-33-activated Tregs produce higher levels of cytokines, TGF-β and IL-10, which promote chronic inflammation and early cancer development while inhibiting the recruitment of antitumor cytotoxic CD8+ T cells." (PMID 40579434, 2025). "For instance, a study has shown that the macrophage-derived soluble glycoprotein NMB (GPNMB) induces cancer stemness and metastasis via CD44 and IL-33." (PMID 41174767, 2025). "GPNMB in TME is mainly expressed by TAMs, can be cleaved into a soluble form by ADAM10 which then binds to CD44 receptor in cancer cells to induce release several chemokines (CXCL1, CXCL2, CCL2, CCL5 and CCL7) as well as cytokines (IL-6, IL-11, and IL-33)." (PMID 38935134, 2024). "In our comprehensive study on IL33 in HCC, we observed its differential expression across cancers, implicating its role in cancer development." (PMID 38923705, 2024). "IL33 is correlated with the survival of HCC patients, indicating potential prognostic value and highlighting its broader implications in cancer biology." (PMID 38923705, 2024). "Here, in our comprehensive study on IL33 in HCC, we observed its differential expression across cancers, implicating its role in cancer development." (PMID 38923705, 2024). "Previous studies have identified IRF3 as a regulator of IL-33 in vitro; however, we demonstrate that IL-33 is the target of TBK1-IRF3 signaling activation in cancer-prone chronic inflammation." (PMID 38816352, 2024). "The correlation between IL33 and immune‐related molecules was illustrated, along with the correlation between TMB and IL33 in pan‐cancer." (PMID 38923705, 2024). "Recent studies underscore the nuanced role of IL‐33 in HCC, one of the most prevalent and lethal cancers worldwide." (PMID 38923705, 2024).
cancer (continued). "In addition, the crosstalk between IL-33, cancer cells and immune cells in SCC remains unknown." (PMID 38662248, 2024). "Studies evaluating the expression of classic pro-inflammatory cytokines (TNF-α, IL-1β, IL-6, IL-17, IL-18, IL-33) in the spinal cord, PAG, and DRG revealed upregulation following inoculation of cancer cells to establish the BCP models." (PMID 38940936, 2024). "Cancer cells can stimulate the expression of lncRNA-CAF in CAFs, which in turn enhances the release of IL-33 and the proliferation of cancer cells." (PMID 37221555, 2023). "The expression levels of genes involved in cancer invasiveness (MYC, VEGFB, IL33, PTGS2, and PTGER2) were increased." (PMID 37601099, 2023). "In mouse models, the expression of metastasis-related molecules, such as CCL2, was upregulated by IL-33, indicating its ability to promote invasion and migration in ESCC as well as in other cancers." (PMID 37296602, 2023). "Pharmacologic inhibition or genetic deletion of PPARγ in ILC2s abolished IL33-induced Th2 cytokine production and tumor growth in vivo, suggesting PPARγ inhibition as a target for ILC2-driven diseases beyond cancer (e.g., asthma, allergy)." (PMID 37686465, 2023). "In this study, other cytokines of importance to cancer that were upregulated upon the use of cannabigerol included IL-28A, CCL22, FGF-21, and IL-33." (PMID 36923728, 2022). "Endogenous IL-33 promotes effector CD4+ and CD8+ T cell activation and IFN-γ production to enhance antitumor responses and suppress cancer growth and metastasis in mouse models of colon and hepatocellular carcinoma." (PMID 36291105, 2022). "In particular, release of IL33, a member of the IL1 family, from mast cells is a disaster in cancer." (PMID 36211375, 2022). "It remains to be elucidated how IL-33 contributes to the described pro- or anti-tumorigenic functions of ILC2s in CRC and other cancers, and if the cytokine milieu in these tissues allows for IL-33-mediated enhancement of NK cell responses." (PMID 36032129, 2022). "In our previous study, we used an organotypic culture to investigate CAFs that promote the aggressive behavior of cancer cells and the paracrine effect of CAF-induced IL-33, which increases the aggressiveness of HNSCCs." (PMID 34298657, 2021). "The expression level of IL-33 and ST2 in tumors has also been considered as a biomarker for patient prognosis in various cancer types." (PMID 34209038, 2021). "Therefore, we aimed to establish stable clones of the IL-33-overexpressing HNSCC cells and an animal model to confirm whether IL-33 exerts an autocrine effect on cancer cells in addition to the paracrine effect of CAF-induced IL-33, which increases the aggressiveness of HNSCC." (PMID 34298657, 2021). "Because IL‐33 and MMP‐9 are often highly expressed in various tumors, this immunosuppressive mechanism most likely exists in other cancer types." (PMID 34486239, 2021). "IL-33 is able to increase PD-1 and PD-L1 expression at the surface of CD8+ T lymphocytes and cancer cells, respectively." (PMID 34572318, 2021). "Thus, IL‐33 could act as a novel target for cancer immunotherapies." (PMID 33305406, 2021). "The data supports a new paradigm for cancer immunology, where the IL-33/ILC2 axis enhances additional TH1 effector function that assists and mediates anti-cancer CTL immune responses and reduces tumour metastasis." (PMID 34112824, 2021). "In this study, IL-33 promoted migration and invasion of the cancer cells through the induction of EMT, and the levels of IL-33 in CAFs and cancer cells were correlated with the severity of invasiveness of the HNSCC." (PMID 34209038, 2021). "Recent studies suggest that IL33/IL33Rα is involved in HNSCC carcinogenesis, possibly through both direct effects on the cancer cells and indirect effects via stromal/immunocompetent cells." (PMID 33066437, 2020). "Proinflammatory interleukin-33 (IL-33) binds to its receptor ST2L and is involved in inflammation and the malignant behavior of cancer cells." (PMID 32340025, 2020).